PRDX6 (peroxiredoxin 6)
Diseases named in the same sentence as PRDX6 in open-access papers (continued):
Sharing a sentence is not in itself a finding about the gene and the disease.
cancer (continued). "For instance, there were approximately 360 colonies in the PRDX6 overexpression group when single cancer cells were planted over a 4-week period, which was obviously increasing compared with the control group." (PMID 32201510, 2020). "PRDX6 is highly expressed in a variety of cancer cells, including lung, ovarian, tongue, and breast cancer 11-14." (PMID 32201510, 2020). "In our study, PRDX6 was also found to have an inhibitory role in the apoptosis of SiHa cells, demonstrating an obvious apoptosis inhibition of cancer cells following overexpression." (PMID 32201510, 2020). "A notable elevation of Prdx6 level has been detected in many cancer species, many of which have high radioresistance." (PMID 30621289, 2019). "Together, these findings reveal the miR-371-3p target gene PRDX6 as a key regulator of the reversible drug tolerance that frequently emerges within heterogeneous cancer cell populations." (PMID 27484502, 2016). "Here, the authors identify miR-371-3p as a suppressor of drug tolerance in cancer cell lines by its target gene PRDX6, which in turn regulates PLA2/PKCα signalling and ROS levels." (PMID 27484502, 2016). "Consistent with the inhibitory effect on luciferase activity, the expression of PRDX6 was also decreased by thiacremonone in cancer cells." (PMID 24618722, 2014). "The inhibitory effect of thiacremonone on cancer cell growth is reversed by mutant PRDX6 (C47S), and expression and activity of PRDX6 is also reversed." (PMID 24618722, 2014). "Prdx6 is a member of the PRDX family, associated with functions such as cell proliferation, differentiation, and apoptosis, thus executing anti-cancer activity." (PMID 21857934, 2011). "As an additional point, it remains undetermined whether PRDX6 is functionally involved in regulation of the SASP in cancer cells per se." (PMID 40265973, 2025). "Efforts have been made to identify PRDX6 inhibitors for cancer treatment." (PMID 39887931, 2025). "We found that patients harboring cancers with high expression of PRDX6 have a poor prognosis." (PMID 38867112, 2024). "Taken together, the present results suggest that PRDX6 may be an alternative target for anti-cancer drugs, with fewer side effects." (PMID 38867112, 2024). "In addition, several studies have reported that high expression of PRDX6 plays an important role in cancer initiation or metastasis." (PMID 38544826, 2024). "Previous studies showed that TPI1 and PRDX6 protein played a critical role in cancer cells." (PMID 38577609, 2024). "Moreover, it has been reported that PRDX6 is highly expressed in cancer tissues, such as colon cancer and cervical cancer." (PMID 38544826, 2024). "CDKN2A displayed higher mutation rates across multiple cancer types (31%), and other frequently mutated genes included LRPPRC (13%), PRKAA2 (11%), VLDLR (9%), ASNS (8%), GZMA (7%), GLS (7%), TNFRSF1A (6%), PSAT1 (5%), and PRDX6 (4%)." (PMID 37534256, 2023). "Third, PRDX6 promotes the development of several cancer cells." (PMID 37521469, 2023). "PRDX6 promotes certain cancers' progression through its GPX and iPLA2 activities." (PMID 35258176, 2022). "This makes it more difficult to study the cancer-promoting mechanism of PRDX6." (PMID 36209344, 2022). "In NSCLC, PRDX6 over-expression promotes cancer cell proliferation and invasive phenotype." (PMID 36361777, 2022). "Then, the results so far obtained suggested that the interaction between FTH1/PRDX6 in cancer cells might alter cell proliferation and migration, leading to a less invasive phenotype." (PMID 36361777, 2022). "PRDX6 may promote cancer in ICC by regulating this pathway, but the specific regulatory mechanism is unclear." (PMID 36209344, 2022). "Sequencing results showed that Wnt7a, Wnt7b, Fzd2, Mmp7 and Ccnd2 in the Wnt signaling pathway were downregulated after PRDX6 knockout, suggesting that this signaling pathway may be involved in the regulation of PRDX6's cancer-promoting effect." (PMID 36209344, 2022).
cancer (continued). "We found that the expression of PRDX6 was higher in cancer tissues than in peritumoral tissues." (PMID 36209344, 2022). "In a word, we not only uncover the pivotal roles of the PRDXs in the progression of 33 types of cancer, but validate that knocking down PRDX6 could attenuate the cell growth through JAK2-STAT3 pathway in BLCA." (PMID 34246267, 2021). "Furthermore, knocking down of PRDX6 inhibited growth of cancer cells through the JAK2-STAT3 in bladder cell lines." (PMID 34246267, 2021). "Higher expression of PRDX1 while lower expression of PRDX6 was shown in the colonospheres than their parental cancer cells (HT29), consistent with their expressional differences between normal colon tissues and COAD tumors, indicating their potential functions in driving COAD tumorigenesis." (PMID 32231717, 2020). "PRDX6 has been recently proven to be a tumor promoter in a variety of cancers." (PMID 32201510, 2020). "Thus, specific suppression of Prdx6 can be a promising approach in the treatment of some radioresistant types of cancer." (PMID 30621289, 2019). "The role of Prdx6 in cancer cells has been studied previously with conflicting outcomes." (PMID 31652719, 2019). "While increased PRDX6 is described in a number of neurodegenerative diseases and some cancers, only one disease, alcoholic steatitis, reports decreased PRDX6 protein content with a much lesser decrement in PRDX6 than that found for MFM horses (1.6-fold vs. 18-fold)." (PMID 30289745, 2018). "A previous suppression of PRDX6 led to increased ROS levels and apoptosis of cancer cells." (PMID 26888332, 2016). "This promising result points to the usefulness of PRDX6 inhibitors in cancer therapy." (PMID 25594034, 2014). "However, peroxiredoxin-2 and peroxiredoxin-4 of cluster 2, the same ubiquitous family of peroxiredoxin-6, which were up-regulated in many cancers, were shown in an upright “V” shape." (PMID 23890079, 2013). "Notably, although the scientific community remains divided regarding its role in oncogenesis, compelling evidence suggests that PRDX6 exerts substantial influence on cancer initiation and progression across various malignancies, making it a focal point in the present review." (PMID 40298631, 2025). "Despite some differences, the anti-proliferative and anti-migratory effects of its elimination are conserved between cancer cells suggesting that PRDX6 could be considered a key factor in different cell lines, in which its abolition would be a good therapeutic strategy." (PMID 39061949, 2024). "Thus, our results demonstrate a relevant aspect of PRDX6 in cancer cells." (PMID 39061949, 2024). "The observation that loss of PRDX6 does not completely attenuate selenoprotein synthesis may be advantageous with respect to the development of PRDX6 inhibitors as anti-cancer drugs." (PMID 38867112, 2024). "Thus, inhibiting PRDX6 may be an effective strategy for sensitizing cancer cells specifically to iron-triggered ferroptosis." (PMID 38867112, 2024). "Indeed, high levels of PRDX6 contribute to the proliferation of cancer cells." (PMID 36361777, 2022). "In addition, PRDX6 could regulate proliferation of cancer cell via JAK2-STAT3 pathway and involve into the process of cell cycle in BLCA." (PMID 34246267, 2021). "Therefore, our results demonstrated that PRDX6 significantly suppresses cancer cell apoptosis via alterations in Bcl-2 family protein expression and may be related to the mitochondrial pathway." (PMID 32201510, 2020). "However, some other studies showed upregulation of PRDX6 in malignant tumors." (PMID 17980029, 2007). "In this regard, PRDX6, MAGOHB, NUCKS1, DCAF13, and TXN displayed an overall negative correlation with multiple immune checkpoints in LUAD, LUSC, and other cancer types." (PMID 37835514, 2023). "Consistent with this notion, the mouse homologous genes of human PRDX6, MAGOHB, NUCKS1, DCAF13, and TXN were upregulated by taxifolin in LL2 LC tumors and facilitated CTL-derived toxicity towards cancer cells." (PMID 37835514, 2023).
cancer (continued). "The indirect immunofluorescence (IF) microscopy was used to determine the subcellular location of PRDX6 and CANX (species-specific secondary antibodies labelled by Alexa Fluor 488, green) in human cancer cell lines." (PMID 36120430, 2022). "Cancer cells were pretreated with AP-1 inhibitor (SR11302, 10 μM) 30 min prior to the treatment of SVT (5 μg/ml), and then assayed cell growth and PRDX6 expression." (PMID 26061816, 2015). "As PRDX6 scavenge peroxide, such as small H2O2, it supports survival of cancer cells and tumor maintenance." (PMID 24618722, 2014). "For the first time, our paper describes EIF4A1, CLIC1, PRDX6, CLIC4, ENO1, ANXA4, EMD and Ku70 in relation to EEC, although their role is well established in other cancers." (PMID 22415234, 2012). "Testing gene-gene interactions between PRDX6 and GSTpi would be an interesting future direction both in ALI and other diseases such as cancer." (PMID 21627785, 2011). "Therefore, we conclude that circ-231 is involved in migration and proliferation of cancer cells through mediating the synthesis of TPI1 and PRDX6 proteins." (PMID 38577609, 2024). "Here, we describe PRDX6 knockdown as a potential FIN, reinforcing its nomination as a target to sensitize tumor cells to ferroptosis and to complement and potentiate conventional cancer therapies." (PMID 39601357, 2024). "PRDX6 (peroxiredoxin 6) and TXN (thioredoxin) are known for their antioxidant activities, and TXN enhances NK cell-derived anti-cancer immunity in the tumor microenvironment (TME), suggesting a potential for their inductions to contribute to taxifolin’s antioxidant actions." (PMID 37835514, 2023). "Immunofluorescence analysis showed that PRDX6 was expressed in cancer cells and macrophages, but not in hepatic stellate cells." (PMID 36209344, 2022). "Immunofluorescence showed that PRDX6 was expressed in cancer cells and ICC macrophages, but not in hepatic stellate cells." (PMID 36209344, 2022). "Immunofluorescence showed that PRDX6 was expressed in cancer cells and macrophages in ICC, but not in hepatic stellate cells." (PMID 36209344, 2022). "PRDX6 may promote the occurrence and development of ICC by regulating Wnt7a/Mmp7 in cancer cells and Wnt7b/Ccnd2 in macrophages." (PMID 36209344, 2022). "AA production and NOX2 activation was also involved in stimulation of metastasis by Prdx6 PLA2 activity in several cancer models, although in another study, NOX2 activation was shown to proceed through Prdx6 mediated lysophosphatidic acid (LPA) receptor activation." (PMID 31652719, 2019). "Recent studies suggest that PRDX6 is a predicative biomarker for the prognosis of patients with malignant tumors; however, there is no consensus on the results." (PMID 30104402, 2018). "Indeed, knockdown of PRDX6, PLCβ4 or STX12 in five additional cancer cell lines similarly affected DTP formation." (PMID 27484502, 2016). "This study highlighted the critical role of PRDX6 in BRCA progression, particularly its ability to promote mitochondrial biogenesis and OXPHOS through both TFAM‐dependent and ‐independent pathways, thereby enhancing cancer cell proliferation, migration, and invasion." (PMID 40583735, 2025). "Although the noncanonical PLA2 and LPCAT activities were also characterized for PRDX6, whether PRDXs exhibit nonenzymatic function in cancer remains unknown." (PMID 39887931, 2025). "Among these proteins, some have not been studied to be relevant to carcinoma medicine resistance before, like PRDX6, and could be new multidrug-resistance relevant proteins." (PMID 35509845, 2022). "While it is well‐established that PRDX6 can mitigate oxidative stress‐induced mitochondrial damage through its unique iPLA2 and GPx activities, our results indicated that PRDX6 may also induce mitochondria into an active state of biogenesis and OXPHOS to meet the high energy demands of cancer cells." (PMID 40583735, 2025).
cancer (continued). "Moreover, experiments in vitro showed that PRDX6 could regulate cell proliferation via JAK2-STAT3 signaling and involve the cell cycle process in BLCA, which may be more valuable for personalized treatment of cancer." (PMID 34246267, 2021). "We observed that TPI1 or PRDX6 knockdown resulted in the inhibition of the migration and proliferation of cancer cells and the knockdown inhibited the migration of cancer cells, although, in KYSE150, the proliferation of cancer cells was not altered after PRDX6 knockdown." (PMID 38577609, 2024).
tumor (61 papers, 2007 to 2026). "Overexpression of PRDX4 and PRDX6 was associated with advanced tumour stage, larger tumour size, higher immune scores, and increased immune cell infiltration." (PMID 41761027, 2026). "PRDX6, which has been associated with tumor progression, is primarily found in the cytoplasm, as we demonstrated, but it can move to compromised mitochondrial membranes to reduce ROS levels." (PMID 39594421, 2024). "The PS2 mutation inhibits the aiPLA2 activity of Prdx6 through the γ-secretase cleavage mechanism to suppress lung-tumor development." (PMID 38671897, 2024). "In lung tumor model, peroxiredoxin 6 (PRDX6) contributes to tumor growth, which is associated with JAK2/STAT3 pathway." (PMID 37214475, 2023). "Analysis of PRDX6 protein expression levels combined with clinicopathological data indicated that PRDX6 was associated with tumor differentiation, tumor number and TNM stage." (PMID 36209344, 2022). "Notably, BRCA patients showed a higher frequency of simultaneous mutations in MGST3, NDUFS2, and PRDX6, while co-occurring mutations were less frequent in other tumor types." (PMID 39594421, 2024). "We found that NR4A1 suppressed tumor growth in BC by antagonizing the c-Fos-mediated transcriptional activation of PRDX6, a bifunctional enzyme involved in cellular lipid and redox homeostasis." (PMID 40164686, 2025). "The results revealed that PRDX6 expression was significantly higher in normal tissues than in tumor tissues (p = 4.59e‐20)." (PMID 40583735, 2025). "Other targets included Filaggrin-2, peroxiredoxin 6, Calmodulin-like protein 5, TBCEL-TECTA readthrough protein, Desmocollin 1 and 3, and Desmoplakin variant protein—with implications in diagnosis and tumour progression." (PMID 40725142, 2025). "Both NRF2 and peroxiredoxin 6 were significantly overexpressed in tumor tissue compared with healthy tissue (p = 0.02 and p = 0.02, respectively)." (PMID 41187427, 2025). "For a given patient, prior to any treatment, NRF2 and peroxiredoxin 6 are overexpressed in tumor tissue compared with healthy tissue." (PMID 41187427, 2025). "We compared NRF2 and peroxiredoxin 6 expression between healthy and tumor tissues using biopsies from six representative patients." (PMID 41187427, 2025). "•NRF2 and peroxiredoxin 6 are overexpressed in tumor tissue compared to healthy tissue prior to any treatment, suggesting their involvement in therapy resistance." (PMID 41187427, 2025). "Compared to the control group, overexpression of PRDX6 significantly increased both tumor volume and weight." (PMID 40583735, 2025). "This is reflected in the fact that PRDX6 levels correlate differently with patient prognosis depending on the tumor." (PMID 39061949, 2024). "The expression level of PRDX6 mRNA was much higher in patients who underwent the tumor resection (P < 0.05)." (PMID 38544826, 2024). "On the other hand, PRDX6 promotes tumor cell proliferation through multiple signaling pathways related to cell proliferation." (PMID 36611974, 2023). "Although there is some evidence linking PRDX6 to tumor progression, how it manages to stop tumor growth and metastasis has not yet been described." (PMID 37371884, 2023). "Our previous studies confirmed that NPM downregulates ROS by antioxidant protein PRDX6 in tumor cells." (PMID 37648688, 2023). "Many studies report increased expression and activity of PRDX6 in the tumor tissues of patients with NSCLC." (PMID 36611974, 2023). "In conclusion, PRDX6 participates in chemotherapy resistance, as well as tumor cell growth and invasion through its anti-oxidant effect and ROS-related signaling pathways." (PMID 36611974, 2023).